RN7SL168P (RNA, 7SL, cytoplasmic 168, pseudogene)
Gene: Miscellaneous RNA gene on chromosome 22 (19,365,766 to 19,366,044, forward strand). Ensembl gene ENSG00000244296.
Homologues: Orthologues: chimpanzee Metazoa_SRP (99% identical), macaque Metazoa_SRP (94% identical). Paralogues in human: RN7SL1 (84% identical), RN7SL296P (84% identical), RN7SL2 (83% identical), RN7SL3 (83% identical), RN7SL322P (82% identical), RN7SL493P (82% identical), RN7SL679P (82% identical), RN7SL566P (81% identical), RN7SL166P (81% identical), RN7SL357P (81% identical), RN7SL45P (81% identical), RN7SL478P (81% identical), and 705 more.